PANX1 (pannexin 1)
Diseases named in the same sentence as PANX1 in open-access papers (continued):
Sharing a sentence is not in itself a finding about the gene and the disease.
COVID-19 (10 papers, 2021 to 2025). A disease caused by infection with severe acute respiratory syndrome coronavirus 2. "All these conditions are present and exacerbated in COVID-19 patients, suggesting that preventing Panx-1 opening could reduce infection and associated inflammation." (PMID 34841222, 2021). "In the future, it will be interesting to determine whether the recent vaccines for COVID-19 can prevent viral entry and Panx-1-associated inflammation or whether both effects could be separated." (PMID 34841222, 2021). "We propose that blocking Panx-1 channels or associated purinergic signaling could prevent the devastating acute and long-term consequences of COVID-19 or other emerging coronaviruses." (PMID 34841222, 2021). "Panx1 has emerged as a key player in the pathogenesis of COVID-19, primarily by mediating ATP release into the extracellular space." (PMID 40978734, 2025). "Lastly, during SARS-CoV-2 infection, prostaglandin E2 (PGE2) was shown to be released via Panx1 channels, contributing to the cytokine storm and pulmonary inflammation observed in COVID-19 patients." (PMID 40978734, 2025). "Due to the widespread Panx1 expression in vertebrates, Panx1 HCs represent a potential target for reducing the inflammatory burden and mitigating the damaging effects of the cytokine storm in COVID-19 patients." (PMID 39990207, 2025). "The impact of Panx1 channels is not limited to pulmonary damage but also extends to systemic inflammation and the cytokine storm characteristic of severe COVID-19 cases." (PMID 40978734, 2025). "In COVID-19, ATP is released by infected cells through pannexin 1 (PANX1) channels as a response to conditions like viral invasion, cell stress, and hypoxia." (PMID 39126095, 2024). "Due to their contribution to inflammation and the link to viral infectious diseases, such as human immunodeficiency virus (HIV) infections and hepatitis C, it seems likely to assume that Panx1 channels can also play a role in COVID-19." (PMID 35628472, 2022). "The involvement of Panx-1 in lungs has been assessed in the context of patients with COVID-19 suffering from hyperinflammation and the Panx-1 channel was shown to open in response to SARS-CoV-2." (PMID 35492217, 2022). "Another FDA-approved drug, spironolactone, has also proven to be a potential Panx-1 blocker in COVID-19 patients." (PMID 35721552, 2022). "The present study was set up to test the effects of drugs previously proposed for the treatment of COVID-19 on Panx1 channels at transcriptional, translational, and functional levels." (PMID 35628472, 2022). "In addition, Panx-1 channel opening is indirectly associated with IL-1β processing and release, suggesting that Panx-1 amplifies inflammation, but its role in COVID-19 pathogenesis is unknown." (PMID 34841222, 2021). "Panx-1 channels participate in several inflammatory conditions exacerbated during COVID-19 pathogenesis, including hypoxia, coagulation, blood pressure, endothelial permeability, and apoptosis." (PMID 34841222, 2021). "Analysis of the cell population expressing Panx-1 mRNA indicates that most cells in the nasal epithelia from COVID-19 patients were positive." (PMID 34841222, 2021). "Analysis of goblet, macrophages, secretory, and developing ciliated cells in uninfected conditions (respectively) compared with COVID-19 samples indicate that these populations were expanded and the expression of Panx-1 mRNA also increased." (PMID 34841222, 2021). "We next conducted immunofluorescence staining for Panx-1 and other cellular markers to determine the expression and distribution in human lung tissue samples using confocal microscopy under control and COVID-19 conditions." (PMID 34841222, 2021). "Analysis of lungs obtained from COVID-19 patients with severe immune-cell-infiltrating pathology and major alveolar wall compromise indicates a significant upregulation of Panx-1 expression in multiple cell types, as predicted from the scRNAseq data." (PMID 34841222, 2021).
COVID-19 (continued). "Lung tissue and nasal swab analysis indicate that Panx-1 mRNA and protein are increased in immune and lung cell populations, supporting the essential role of the Panx-1 channel in COVID-19 pathogenesis." (PMID 34841222, 2021). "This experiment indicates that Panx-1 expression is increased in COVID-19-infected tissues and is widely distributed into multiple cell types, especially in areas with compromised immunity and tissue destruction." (PMID 34841222, 2021). "Additionally, high levels of ATP released through Panx1 have been documented to promote cell apoptosis and endothelial damage, contributing to systemic complications of COVID-19, including coagulopathy and acute respiratory distress syndrome." (PMID 40978734, 2025). "Another receptor, Pannexin-1 (Panx-1), has been found to be critical for COVID-19 pathogenesis." (PMID 37673862, 2023). "Accordingly, several of the drugs previously or currently proposed for COVID-19 treatment could affect Panx1 channels." (PMID 35628472, 2022). "The hypothesis of this study states that drugs formerly repurposed for the treatment of COVID-19 might act through alterations of Panx1 channels." (PMID 35628472, 2022). "This creates new opportunities for the treatment of Panx1-related diseases and also suggests that COVID-19 drug candidacy might be an interesting selection criterion in the search for new drugs targeting Panx1 channels." (PMID 35628472, 2022). "Knowing that the drug is meant for hypertension patients, spironolactone could be beneficial as a Panx-1 blocker in the context of COVID-19." (PMID 35721552, 2022). "Analysis of Panx-1 protein expression indicates that under control conditions (C-Panx-1), Panx-1 expression was moderate, but under COVID-19 conditions, Panx-1 expression increased significantly (CV, Panx-1, p = 0.00153, n = 9 cases with 6 sections per individual)." (PMID 34841222, 2021). "In contrast, Panx-1 expression in COVID-19 cases (n = 9 different individuals with at least 8–12 days in an intensive care unit) exhibits a significant increase in the numbers of cells expressing Panx-1 expression detected in the alveolar wall compared with uninfected lungs." (PMID 34841222, 2021). "Probenecid, a potent Panx-1 inhibitor, has proven to be a promising target of inflammation in different diseases, including COVID-19 pathogenesis, where Panx-1 mRNA expression was responsible for increased ATP and IL-1β levels in human lung epithelial cells infected with SARS-CoV-2." (PMID 35721552, 2022). "Moreover, proteins like P2X7 and Panx-1 may contribute to the pathogenesis of COVID-19." (PMID 37673862, 2023). "However, whether Panx-1 channels and ATP are involved in COVID-19 pathogenesis was unknown." (PMID 34841222, 2021). "Hence, PANX-1 and probenecid (an FDA-approved PANX-1 inhibitor) have been recently suggested for further investigation in the efforts to develop a COVID-19 treatment." (PMID 33602138, 2021). "Furthermore, Panx1 mRNA and protein expression levels were shown to be elevated in samples of patients with a SARS-CoV2 infection, indicating a role of Panx1 channel opening in COVID-19 and suggesting Panx1 channels as potential drug targets." (PMID 35628472, 2022).
hepatocellular carcinoma (10 papers, 2019 to 2025). A malignant tumor that arises from hepatocytes. "Upon stimulation with free fatty acids, rat liver hepatoma-derived cells undergo lipoapoptosis, which goes along with Panx1 channel-mediated ATP release." (PMID 37492223, 2023). "In human hepatoma-derived cells, Panx1 channels control the release of exosomes and microRNAs contributing to liver disease development caused by HCV infection." (PMID 37492223, 2023). "In this study, Panx1 was found to promote the transmembrane transformation of hepatocellular carcinoma cells by promoting the expression of Snai1, an EMT-related transcription factor." (PMID 31737105, 2019). "We established a Panx1 over-expressing hepatocellular carcinoma cell line and found that Panx1 overexpression promotes cell migration and invasion." (PMID 31737105, 2019). "As we know metastasis is the main factor for HCC patients with a poor prognosis, and we speculated that Panx1 may have an related impact on the biological function of hepatocellular carcinoma cells." (PMID 31737105, 2019). "Overexpression of pannexin 1 (PANX1) promoted the invasion and migration of hepatocellular carcinoma cells via modulation of EMT depending on AKT signaling." (PMID 35096011, 2021).
rhabdomyosarcoma (10 papers, 2018 to 2025). A rare aggressive malignant mesenchymal neoplasm arising from skeletal muscle. "As was demonstrated in an earlier study with rhabdomyosarcoma cells, PANX1 mRNA was decreased, but PANX1 protein showed a significantly increased level by quercetin treatment." (PMID 40566630, 2025). "Paradoxically, in mesenchymal-origin rhabdomyosarcoma, Panx1 reduced cell viability and migration through combination with the AHNAK scaffold protein in the pseudopodal protrusion." (PMID 40909173, 2025). "In rhabdomyosarcoma, Panx1 impeded tumor cell proliferation due to interaction with bracket proteins, which stabling cell structure." (PMID 40909173, 2025). "The correlation between AHNAK and PANX1 led to initial insights into the mechanisms by which PANX1 suppresses malignant properties in rhabdomyosarcoma." (PMID 38909013, 2024). "After establishing PANX1 as an important regulator of myogenesis, we investigated its role in rhabdomyosarcoma (RMS), a neoplasm thought to arise from muscle progenitors due to impaired differentiation." (PMID 35194046, 2022). "In the same line a similar response is observed in rhabdomyosarcoma cells, in which inducible expression of PANX1 prevents cell migration." (PMID 34975840, 2021). "Paradoxically, Panx1 exhibits tumor-suppressive functions in rhabdomyosarcoma." (PMID 40909173, 2025). "For instance, in rhabdomyosarcoma, Panx1 re-expression not only decreased cell viability, inhibited migration, and promoted apoptosis, but also exhibited an inhibitory interaction with AHNAK, highlighting its role as a regulator of malignancy in this pediatric sarcoma." (PMID 40978734, 2025). "Thus, at least in this rhabdomyosarcoma model it seems that PANX1 contribution might be related either to cytoskeleton re-organization and signaling, as shown for CX43 C-terminus." (PMID 34975840, 2021). "Interestingly, PANX1 expression induces gene and protein level upregulation of CX43, which has a tumor suppressive role in rhabdomyosarcoma." (PMID 34975840, 2021).
colitis (9 papers, 2014 to 2025). Inflammation of the colon. "In an experimental colitis model, Panx1 was associated with enteric neurons death via caspase activation as also shown here." (PMID 36072579, 2022). "Using a dextran sodium sulfate mouse model of IBD, it is found that compound 12 markedly reduced colitis severity, highlighting new PANX1 inhibitors as a proof‐of‐concept treatment for IBD." (PMID 39739600, 2025). "We found that PANX1, which is upregulated in UC patients, is required for the induction of colitis in multiple experimental models." (PMID 41132681, 2025). "We also examined compound 12 as a proof‐of‐concept approach for treating IBD by using a dextran sodium sulfate (DSS)‐induced mouse model of colitis, further underscoring the potentials of new PANX1 inhibitors in basic and translational research." (PMID 39739600, 2025). "We have found that the damage observed in the colitis model was significantly attenuated when the Panx1 channels were blocked by its inhibitor 10Panx1." (PMID 30127744, 2018). "Previous work using a DSS mouse colitis model has shown that blocking Panx1 and P2X7R function can reduce the tissue damage observed." (PMID 30127744, 2018). "In a mouse model of colitis it was shown that inhibition of P2X7R, Panx1, the adaptor protein apoptosis-associated speck-like protein containing CARD (ASC) or caspase activity attenuated the inflammation process that caused enteric cell death." (PMID 27445679, 2016). "In the present study, by using a human colitis model adapted from previous studies, we aimed to determine whether inhibition of Panx1 and/or P2X7R function will prevent cytokines-induced inflammation in the mucosal layer of the human colon." (PMID 30127744, 2018). "For instance, in the DSS mouse model of colitis, ATP released from CBX sensitive Panx1 channels activates P2X7R leading to inflammasome formation and NF-κB signaling." (PMID 30127744, 2018). "Our further studies have showed that inhibition of ATP release by pharmacological inhibitor of ATP transporters including PANX1, i.e. CBX, dampens extracellular ATP levels, resulting in amelioration of DSS-induced colitis." (PMID 26739809, 2016). "Proinflammatory cytokines TNFα and IL-1β (each 10 ng/mL) were used to induce colitis in mucosal strips, and the effects of Panx1 and P2X7R on cytokines-induced tissue damage were determined in the presence of the Panx1 channel blocker 10Panx1 (100 μM) and P2X7R antagonist A438079 (100 μM)." (PMID 30127744, 2018). "Hence, the aim of the present study was to investigate the function of Panx1 and P2X7R in an ex vivo colitis model developed from human colonic mucosal explants." (PMID 30127744, 2018). "Thus, we treated TNBS-induced experimental colitis with HPM to investigate the molecular mechanism by which HPM regulates the colonic NLRP3 inflammasome by observing the ATP content and the expression of P2X7R, Pannexin-1 and NF-κBp65." (PMID 34043726, 2021).
ischemic stroke (9 papers, 2012 to 2025). A stroke disorder caused by obstruction of blood flow to the brain, due to thrombotic (local blood clot formation) or embolic (due to a blood clot or other material traveling from another site) event. "The discovery of lysophospholipids as a common stimulus for Panx1 and Panx2 may underlie the proposed compensatory roles between Panx1 and Panx2 described in ischemic stroke and insulin secretion from β-cells." (PMID 40309905, 2025). "PANX1 has received increasing attention due to its close association with various diseases associated with the central nervous system, especially for its role in inflammation after ischemic stroke." (PMID 37196132, 2024). "The difference in ischemic stroke outcomes associated with gender may have been caused by higher levels of PANX1 channels in female mice than in male mice, while the deletion of PANX1 channels in females considerably countered the deleterious effects of PANX1 channels." (PMID 37196132, 2024). "The membrane channel protein Panx1 is a promising therapeutic target since its involvement was demonstrated in a variety of pathologies such as neuropathic pain, ischemic stroke and cancer." (PMID 40430343, 2025). "In this respect, the PANX1 channel has been reported to contribute to chronic neuropathic pain and ischemic stroke." (PMID 37196132, 2024). "During the acute phase of ischemic stroke, PANX1 channels in microglia and astrocytes are activated to release ATP extracellularly to produce various pro-inflammatory factors such as IL-1 and IL-18." (PMID 37196132, 2024). "Probenecid, as a specific pannexin-1 inhibitor, has been proven to protect against ischemic stroke by reducing inflammation and brain edema." (PMID 35401398, 2022). "Emerging evidence reveals the pathological activity of pannexin-1 in contributing to disease processes that include ischemic stroke, seizure, spinal cord injury, and tumor formation." (PMID 35401398, 2022). "In models of ischemic stroke, neuronal death caused by overactivation of NMDAR is also independent of Ca2+ influx, but dependent on signaling complexes formed by NMDARs, Src kinase, and Panx1." (PMID 33661095, 2021). "Thus, Panx1 plays a significant role in ischemic pathology of the retina, which evidently differs from ischemic stroke in the brain, as reported recently." (PMID 22384122, 2012).
Hypertension (8 papers, 2017 to 2025). The presence of chronic increased pressure in the systemic arterial system. "Cardiac hypertrophy is frequently associated with hypertension, and has been previously reported in the Cx40−/− mouse, thus arterial blood pressure was assessed in WT, Cx40−/−, Panx1−/−, and Cx40−/−Panx1−/− mice via carotid pressure transducer catheterization." (PMID 30745457, 2019). "Recently, inhibition of pannexin 1 channels by the steroidal MRA spironolactone was shown to be a novel mechanism for reducing hypertension." (PMID 35837290, 2022). "Additional investigation is needed to ascertain whether the opening of Panx1 channels in mesangial cells occurs during hypertension and its implications for the pathogenesis and progression of CKD." (PMID 38660621, 2024). "Likewise, both the Cx40−/− and Cx40−/−Panx1−/− mice demonstrated similar levels of hypertension, while Panx1−/− mice were normotensive." (PMID 30745457, 2019). "This Panx-1-dependent signaling pathway is likely to play a critical role in the tonic, endothelial control of arterial blood pressure and, therefore, may contribute to the design of new therapeutic strategies for the treatment of cardiovascular-related diseases such as hypertension." (PMID 33688389, 2021). "Connexins and Panx1 have been studied using the inhibitors carbenoxolone, probenecid, and spironolactone, which are also FDA-approved drugs for the management of tracheal ulcers, gouty arthritis and hypertension, respectively." (PMID 33818243, 2021). "Cx40-deficient mice have impaired vasodilation of aortic segments, leading to hypertension, a phenotype not observed in Panx1−/- mice." (PMID 33818243, 2021). "In the current study, despite observing similar levels of hypertension and EC-mediated dysfunction between Cx40−/− and Cx40−/−Panx1−/− mice, kidney renin expression and plasma renin activity were enhanced in mice lacking both Cx40 and Panx1 compared with Cx40−/− mice." (PMID 30745457, 2019).